MIF (macrophage migration inhibitory factor)
Diseases named in the same sentence as MIF in open-access papers (continued):
Sharing a sentence is not in itself a finding about the gene and the disease.
sarcoidosis (6 papers, 2013 to 2024). Sarcoidosis is a multisystemic disorder of unknown cause characterized by the formation of immune granulomas in involved organs. "In this work, we investigated the potential association of serum MIF and several important cytokines with sarcoidosis clinical features." (PMID 36207373, 2022). "As our current data in sarcoidosis indicate that MIF levels are positively associated with IFN-γ and IL-10, but negatively associated with IgG level." (PMID 36207373, 2022). "We evaluated MIF in the serum and bronchoalveolar lavage (BAL) fluid of sarcoidosis patients in association with clinical features and cytokines, IL-18, IL-10, IL-6, IFN-γ." (PMID 36207373, 2022). "To understand the regulation of group of cytokines implicated in sarcoidosis, we assessed the levels of IL-6, IL-18, IFN-γ and MIF in the serum samples of sarcoidosis patients (n = 65) and healthy controls (n = 28) via ELISA." (PMID 36207373, 2022). "Because of wide distribution of MIF among sarcoidosis, we asked if there is a difference between subjects with elevated MIF versus subjects with unmeasurable or low MIF group in regards to cytokine values." (PMID 36207373, 2022). "We identified a group of sarcoidosis patients with lower MIF levels, whereas another group of patients exhibited significantly higher serum MIF levels." (PMID 36207373, 2022). "We investigated if MIF levels can explain, at least in part, the phenotypic diversity in sarcoidosis patients." (PMID 36207373, 2022). "Here, we advance our knowledge by identifying MIF as a systemic modulator of cytokine spectrum and clinical phenotype in sarcoidosis." (PMID 36207373, 2022). "The Box plot indicates a wide distribution of MIF values among sarcoidosis patients." (PMID 36207373, 2022). "The median value of MIF levels in sarcoidosis patients were 130 pg/mL." (PMID 36207373, 2022). "Here, we found that there is a significant heterogeneity among sarcoidosis patients with respect to serum cytokine profile, including IL-18, IFN-γ, IL-10 and MIF." (PMID 36207373, 2022). "Further experimental studies need to elucidate the MIF role in IL-10 and IFN-γ as well as B cell function in sarcoidosis." (PMID 36207373, 2022). "Our study indicate that MIF has as a potential modulatory role in cytokine network and not necessarily detrimental in sarcoidosis." (PMID 36207373, 2022).
sarcopenia (6 papers, 2018 to 2025). Progressive decline in muscle mass due to aging which results in decreased functional capacity of muscles. "Since sarcopenia is associated with high inflammation, we speculated that the circulating MIF levels may reflect the skeletal muscle weakness and atrophy in the elderly with varying degrees of sarcopenia." (PMID 33883602, 2021). "Accordingly, patients with COPD and CHF who had higher inflammatory cytokines and advanced sarcopenia, also expressed higher circulating levels of MIF." (PMID 33883602, 2021). "Interleukin 6, secreted protein acidic and rich in cysteine, macrophage migration inhibitory factor, and insulin-like growth factor 1 levels differed significantly between the normal and sarcopenia groups." (PMID 29872072, 2018). "In general, the categories with sarcopenia status (SPPB score ≤ 8 or SARC-F score ≥ 4) were associated with higher levels of P3NP, CAF22, osteonectin, FABP3 and MIF and lower levels of irisin in the individual cohorts of healthy controls, COPD and CHF patients." (PMID 33883602, 2021). "We hypothesize that the metabolic status in sarcopenia may be reflected in circulating MIF levels." (PMID 38684784, 2024). "Among various candidates investigated, circulating levels of P3NP, CAF22, osteonectin, irisin, FABP3 and MIF were significantly different in the COPF and CHF subjects with advanced sarcopenia, when compared to age-matched healthy controls." (PMID 33883602, 2021). "Based on the collective results, IL-6, SPARC, MIF and IGF-1 were selected for analysis as potential biomarkers for sarcopenia." (PMID 29872072, 2018). "Similarly, serum concentrations of SPARC and MIF were higher in the sarcopenia than the normal group (531.5 ± 40.65 versus 409.4 ± 35.47 pg/mL SPARC, p = 0.047, and 25.10 ± 1.19 versus 20.71 ± 0.89 ng/mL MIF, p = 0.008)." (PMID 29872072, 2018). "Among the candidates investigated, serum levels of IL-6, SPARC, MIF and IGF-1 were significantly different between normal and sarcopenia groups, but not the other biomarkers (data not shown)." (PMID 29872072, 2018).
systemic inflammatory response syndrome (6 papers, 2009 to 2025). SIRS is a serious condition related to systemic inflammation, organ dysfunction, and organ failure. "Macrophage migration inhibitory factor (MIF) plays a crucial role in the occurrence and development of systemic inflammatory response syndrome (SIRS)." (PMID 40595050, 2025). "IL-6 and MIF had the best predicting value in discriminating mild from severe forms, as well as the development of systemic complications (systemic inflammatory response syndrome—SIRS and multiple organ failure—MOF) and fatal outcomes." (PMID 39125854, 2024). "Since the development of systemic inflammatory response syndrome and subsequent development of multiple organ dysfunction syndrome appear to be related to MIF levels and the balance of Th1 and Th2 function, this might be an explanation for the observed kinetic." (PMID 27313864, 2016). "Yet, so far the exact cause of death in murine African trypanosomiasis is unknown and is suggested to be due to Systemic Inflammatory Response Syndrome (SIRS), thus likely multifactorial and going beyond the role of MIF." (PMID 25255103, 2014).
toxoplasmosis (6 papers, 2011 to 2021). A parasitic disease contracted by the ingestion or fetal transmission of toxoplasma gondii. "Recent studies in our laboratory suggest a role for MIF in inducing DC maturation from spleen or mesenteric lymph nodes during experimental toxoplasmosis." (PMID 27057101, 2016). "It has been recently shown in a model of toxoplasmosis induced by intraperitoneal route that MIF is essentially protective." (PMID 21977228, 2011). "Similar to previous studies, we confirmed a central role of MIF in the control of parasite burden in different models of experimental toxoplasmosis." (PMID 21977228, 2011). "Our group have reported the importance of MIF in congenital and acquired toxoplasmosis." (PMID 33552033, 2020). "Because our results indicated that systemic MIF levels are critical for resistance and induction of TipDCs during acute toxoplasmosis, we confirmed these data by administration (via i.p.) of rMIF into Mif−/− mice (0.5 μg per mouse) daily during the first 5 days after T. gondii infection." (PMID 27057101, 2016). "Interestingly, infected Mif−/− mice displayed reduced numbers of TipDCs (5 days after infection) compared to infected WT mice, indicating a novel role for MIF in inducing TipDCs during experimental toxoplasmosis." (PMID 27057101, 2016). "Thus, we propose that MIF actually exerts a bidirectional role in toxoplasmosis." (PMID 21977228, 2011). "T. gondii vaccines expressing the macrophage migration inhibitory factor (MIF) significantly protected immunized mice against acute and chronic toxoplasmosis upon a challenge infection with RH tachyzoites and PRU cysts." (PMID 33919060, 2021). "Previous studies have reported the importance of macrophage migration inhibitory factor (MIF) in congenital and acquired toxoplasmosis." (PMID 29867817, 2018).
allergic asthma (5 papers, 2016 to 2025). A asthma with a basis in a pathological type I hypersensitivity reaction. "We have previously shown that macrophage migration inhibitory factor (MIF)‐licensed MSCs exerted significantly enhanced therapeutic efficacy in reducing inflammation in house dust mite (HDM)‐driven allergic asthma." (PMID 39502000, 2025). "In order to investigate the potential connection between STEAP4 levels and the development of allergic asthma and MIF levels, rAAV6-STEAP4 was injected into the airways of sensitized mice using a pulmonary administration device." (PMID 39176391, 2024). "On the other hand, MIF enhances MSCs’ immunosuppressive properties in various models, such as myocardial repair and allergic asthma." (PMID 39769050, 2024). "We have previously shown that CD74 is required for MIF‐licensed MSC immunomodulation and to significantly increase the retention of human BM‐MSCs in vivo in an HDM model of allergic asthma." (PMID 39502000, 2025). "Previously, we have demonstrated that MIF can promote the expansion and immunosuppressive function of human BM‐MSCs in vitro and significantly increase the retention of human BM‐MSCs in vivo in an HDM model of allergic asthma." (PMID 39502000, 2025).
ankylosing spondylitis (5 papers, 2014 to 2026). An autoimmune chronic inflammatory disorder characterized by inflammation in the vertebral joints of the spine and sacroiliac joints. "It has even been documented that MIF induces TNF production in monocytes, activates β-catenin in osteoblasts and promotes the mineralization of osteoblasts, indicating that the MIF/CD74 axis is linked to inflammation and new bone formation seen in ankylosing spondylitis." (PMID 34621738, 2021).
aortic aneurysm (5 papers, 2021 to 2025). A ruptured aneurysm located in the wall of the proximal portion of the descending aorta proceeding from the arch of the aorta. "We also noticed the high communication probability of MIF signaling from contractile VSMCs, T-cell-like VSMCs, and macrophage-like VSMCs to B cells, which may be associated with B cell infiltration in aortic aneurysms." (PMID 35837612, 2022). "Recent work demonstrated that secretory VSMCs enhance immune cell function via MIF, recruiting immune cell infiltration into the arterial wall and promoting aortic aneurysm growth." (PMID 41383630, 2025). "We observed significant upregulation of MIF mRNA in UIAs, consistent with reports in aortic aneurysms." (PMID 41383630, 2025). "MIF signaling from T cells promoted the transformation of contractile VSMCs to macrophage-like VSMCs; MIF signaling from VSMCs recruited immune cells (especially B cells) into aortic aneurysms." (PMID 35837612, 2022). "Therefore, in aortic aneurysms, MIF from T cells plays a role in promoting the transformation of VSMCs to macrophage-like VSMCs, while MIF from VSMCs recruits immune cells (especially B cells) into aortic aneurysms." (PMID 35837612, 2022). "MIF has been demonstrated to trigger the dedifferentiation of vascular smooth muscle cells (VSMCs), and the latter is closely related with aortic dissection and dissecting aortic aneurysm." (PMID 35096998, 2021). "Meanwhile, MIF signaling was produced by different cell populations and received by different cell populations in the human TAA group and Ang II-induced aortic aneurysm." (PMID 36703732, 2022). "MIF, galectin, CXCL, complement, and chemerin all mediated the migration and recruitment of immune cells into aortic aneurysms." (PMID 35837612, 2022). "Signaling macrophage migration inhibitory factor (MIF), galectin, and C-X-C motif chemokine ligand (CXCL) showed high information flow of intercellular communication, while signaling complement and chemerin were completely turned on in aortic aneurysms." (PMID 35837612, 2022). "MIF and SPP1 signaling networks participated in aortic aneurysm in both organisms." (PMID 36703732, 2022). "Signaling MIF, galectin, and CXCL showed high information flow of intercellular communication, while signaling complement and chemerin were completely turned on in aortic aneurysms." (PMID 35837612, 2022). "Signaling MIF, galectin, CXCL, chemerin, and complement made a significant contribution to aortic aneurysm progression through activating immune cells and promoting immune cell migration, which could serve as the potential target for the treatment of aortic aneurysms." (PMID 35837612, 2022).
autosomal dominant polycystic kidney disease (5 papers, 2016 to 2024). Autosomal dominant form of polycystic kidney disease. "As an inflammatory cytokine, MIF is involved in the carcinogenesis of many cancer types and autosomal dominant polycystic kidney disease (ADPKD)." (PMID 38052787, 2023). "Macrophage migration inhibitory factor (MIF) has long been recognized as a secreted cytokine in the pathogenesis of various human diseases, including cancer and autosomal dominant polycystic kidney disease (ADPKD)." (PMID 38052787, 2023).
B-cell lymphoma (5 papers, 2007 to 2021). "It has been shown in a lymphoma mouse model that loss of MIF markedly delays the onset of B-cell lymphoma development in vivo." (PMID 17470266, 2007). "The bulk of studies investigating MIF in B cell biology have stemmed from those evaluating the functional significance of the MIF/CD74 interaction in B cell lymphoma." (PMID 33324425, 2020). "Less clear from these findings in B cell lymphoma is whether MIF/CD74 interactions are important in de novo B cell antibody responses and/or anti-tumor immunity." (PMID 33324425, 2020). "These cancer studies use anti-CD74-based antibody-drug conjugates to increase drug uptake or monoclonal antibodies against MIF or CD74 in cancers, including metastatic colon cancer, B-cell lymphoma, and other solid malignancies." (PMID 35036405, 2021).
bronchopulmonary dysplasia (5 papers, 2013 to 2020). Bronchopulmonary dysplasia is a chronic respiratory disease that results from complications related to lung injury during the treatment of infant acute respiratory distress syndrome in low-birth-weight premature infants or from abnormal lung development in older infants. "Macrophage migration inhibitory factor (MIF) has been implicated as a protective factor in the development of bronchopulmonary dysplasia (BPD) and is known to be regulated by MicroRNA-451 (miR-451)." (PMID 32321512, 2020). "In very preterm infants, lower levels of MIF and DDT on postnatal day 6 were associated with an increased risk of developing bronchopulmonary dysplasia and late-onset neonatal sepsis." (PMID 28179905, 2017). "Moreover, we correlated MIF and DDT levels with inflammatory and clinical parameters and outcome in very preterm infants who are at risk of developing severe complications including bronchopulmonary dysplasia (BPD) and late-onset neonatal sepsis (LOS)." (PMID 28179905, 2017). "The role and mechanism of action of MIF in bronchopulmonary dysplasia (BPD) are not known." (PMID 23448134, 2013).
chronic lymphocytic leukemia (5 papers, 2017 to 2025). "Initial studies by the Shachar group showed that MIF-dependent CD74 activation drives IL-8 expression that acts to sustain chronic lymphocytic leukemia (CLL) cell survival." (PMID 33324425, 2020). "Moreover, MIF/CD74 signaling also activates the NF-κB signaling pathway in chronic lymphocytic leukemia." (PMID 36496973, 2022). "In B-cell chronic lymphocytic leukemia (B-CLL), secreted MIF enhances tumor cell survival via activation of the CD74/CD44–IL8 axis and the ERK pathway." (PMID 40835826, 2025). "It has been reported that activation of Cd74 by MIF can result in upregulation of TAp63, which further leads to increased expression of integrin VLA-4, resulting in enhanced migration and survival of chronic lymphocytic leukemia cells." (PMID 34836197, 2021).
colorectal tumors (5 papers, 2019 to 2025). "In sum, our therapeutic proof-of-principle CRC mouse models show that tumor-specific stabilized MIF contributes to tumor-associated macrophage recruitment and vessel formation to maintain colorectal tumors, creating a vulnerability which provide a potential targeting strategy in CRC therapies." (PMID 40835826, 2025). "We further demonstrated in a CRC mouse model with constitutive Mif deletion that MIF is specifically stabilized in tumors and promotes colorectal tumor growth." (PMID 40835826, 2025). "These proof-of-principle experiments demonstrate that established colorectal tumors are critically addicted on stabilized, tumor cell-intrinsic MIF - even in aggressive, malignant stages." (PMID 40835826, 2025). "Previously, we have shown a tumor-specific MIF stabilization in the murine AOM/DSS colorectal tumor model." (PMID 40835826, 2025). "The angiogenesis promoting factor macrophage migration inhibitory factor (MIF) was shown to be stabilized by Hsp90 specifically in colorectal tumor cells in a mouse model." (PMID 36060252, 2022). "By analyzing macrophages and T cell populations infiltrating murine colorectal tumors, we demonstrated the participation of MIF in tumor cell differentiation and the fight of the immune system against tumor development." (PMID 31360118, 2019). "We counted and measured the tumors after 68 days of CRC induction with azoxymethane; during this time, either the presence of MIF slowed down colorectal tumor development in WT mice or tumor growth was enabled in knockout mice." (PMID 31360118, 2019). "In this study, MIF and SLC3A2 were shown to participate in regulating the biological behaviour of colorectal tumour cells and promote the further development of cancer, suggesting that MIF and SLC3A2 might serve as potential biomarkers." (PMID 35567291, 2022).
cutaneous melanoma (5 papers, 2010 to 2020). A primary melanoma arising from atypical melanocytes in the skin. "They studied these entities in the peripheral blood of patients with cutaneous melanoma and showed a wide expression of MIF inside these MTFs." (PMID 31013837, 2019). "In addition, skin melanoma cells express MIF mRNA and produce MIF protein." (PMID 24281172, 2010). "Genomic alterations of MIF, CD74 and CD44 in skin cutaneous melanoma have been investigated based on The Cancer Genome Atlas data sets." (PMID 31013837, 2019). "To date, apart from two studies each using a single cell line the role of MIF in the context of human cutaneous melanoma has not been intensively studied." (PMID 25168062, 2014).